TMEM130 (transmembrane protein 130)
Synonyms: DKFZp761L1417; FLJ42643
Tractability: Antibody: UniProt predicts a signal peptide or a membrane-spanning region; its Gene Ontology location is reachable by antibodies, with medium confidence.
Gene: Protein-coding gene on chromosome 7 (98,846,488 to 98,870,771, reverse strand). Ensembl gene ENSG00000166448.
Subcellular location: Golgi apparatus membrane
Subcellular location (Human Protein Atlas): Golgi apparatus
Gene Ontology:
Molecular function: protein binding
Cellular component: Golgi apparatus; plasma membrane; Golgi membrane
Genetic constraint (gnomAD): Loss-of-function variants: 34 observed, 38.12 expected, observed/expected ratio (o/e) 0.89, 90% interval 0.68 to 1.19. The upper end of that interval is the gene's LOEUF score, 1.19, which puts it in group 5 of 6, group 1 being the genes least tolerant of losing a copy. Missense variants: 541 observed, 558.89 expected, observed/expected ratio (o/e) 0.97, 90% interval 0.9 to 1.04. Synonymous variants: 259 observed, 234.46 expected, observed/expected ratio (o/e) 1.1, 90% interval 1 to 1.22.
Homologues: Orthologues: chimpanzee TMEM130 (99% identical), macaque TMEM130 (92% identical), dog TMEM130 (86% identical), rabbit TMEM130 (84% identical), pig TMEM130 (79% identical), rat Tmem130 (72% identical), mouse Tmem130 (69% identical), guinea pig TMEM130 (69% identical), tropical clawed frog tmem130 (36% identical), zebrafish tmem130 (17% identical). Paralogues in human: GPNMB (20% identical), PMEL (19% identical).
Diseases named in the same sentence as TMEM130 in open-access papers:
TMEM130 is named in the same sentence as 1 disease in open-access papers, as found by Europe PMC text mining. Sharing a sentence is not in itself a finding about the gene and the disease. The quoted sentences say what the papers report.
tumor (2 papers, 2021 to 2024). "In all datasets, the primary source of variation (PC1) was likely associated with tumour purity as demonstrated by the expression of neuronal genes, with neuron marker genes like SLC12A5, TMEM130 and SV2B ranking among the top 50 contributors." (PMID 39382765, 2024). "We further examined the hub gene AS events and hub gene mRNA expression between five paired normal and tumor tissues by qRT-PCR, and found that the PSI of EPB41L2, TMEM130, and SORBS2 were different from tumor to normal." (PMID 34692669, 2021). "Using qRT-PCR, we also verified that the gene AS events SORBS2 were downregulated in tumor tissue, and gene AS events EPB41L2, CELF2, TMEM130, and VCL were upregulated in tumor tissue." (PMID 34692669, 2021).